SETD7 (SET domain containing 7, histone lysine methyltransferase)
Diseases named in the same sentence as SETD7 in open-access papers (continued):
Sharing a sentence is not in itself a finding about the gene and the disease.
cancer (continued). "The aim of this systematic review is to provide an updated description of how SETD7 impacts cancer-related processes in different cell contexts, namely basal growth, upon induction of DNA damage, in hypoxia and oxidative stress." (PMID 35326563, 2022). "Histone–lysine N-methyltransferase SETD7 regulates a variety of cancer-related processes, in a tissue-type and signalling context-dependent manner." (PMID 35326563, 2022). "The most studied cancer-related processes regulated by SETD7 were cell proliferation, apoptosis, epithelial-mesenchymal transition, migration and invasion with special relevance to the pRb/E2F-1 pathway." (PMID 35326563, 2022). "SETD7 mRNA and/or protein expression in human cancer tissue was evaluated using public databases and/or in-house cohorts, but its prognostic significance remains inconclusive." (PMID 35326563, 2022). "miR-153 mRNA was lower in OVCAR-3 and SK-OV-3 cell lines compared to normal ovarian cell lines (NOE095 and hOSEpiC), and SETD7 expression was higher in cancer cells." (PMID 35326563, 2022). "SETD7 consistently prevented epithelial to mesenchymal transition in different cancer types, and inhibition of its function appears to be associated with improved response to DNA-damaging agents in most of the analysed studies." (PMID 35326563, 2022). "Here, we discuss the known SETD7 substrates and their putative roles when methylated by SETD7 in regulation of cell cycle, apoptosis and response to external stimulation in human cancers." (PMID 35812730, 2022). "In this work, we summarised the literature on SETD7 expression and function in cancer, to identify the contexts where SETD7 expression and targeting can lead to improvements in cancer diagnosis and therapy." (PMID 35326563, 2022). "Concordantly, analysis of 60 cases and their adjacent normal tissue showed an inverse correlation between miR-153 and SETD7 mRNA expression, with miR-153 downregulation in the cancer tissue." (PMID 35326563, 2022). "SET domain containing 7(SETD7), a histone lysine methyltransferase, has been reported to be dysregulated in various cancers." (PMID 35125116, 2022). "Amongst the list of potential candidates of ISL1-interacting proteins, we noted the presence of SETD7, which has been reported as a histone H3K4-specific methyltransferase associated with cancer progression." (PMID 30674889, 2019). "In the case of cancer, further studies of the biological and pathological effects of SETD7 can significantly contribute to the development of novel approaches for diagnosis and targeted interventions." (PMID 30013796, 2018). "The involvement of the methyltransferase SETD7 in cell proliferation, differentiation and endoplasmic reticulum (ER) stress makes it a promising therapeutic target for cancer." (PMID 30013796, 2018). "The GSH/GSSG ratio was significantly lower in SETD7-silenced cancer cells than that of control cells, suggesting that SETD7 maintained the reductive status of cells." (PMID 29212211, 2017). "In consistent with GSH/GSSG ratio levels, SETD7 knockdown significantly elevated intracellular ROS levels, suggesting that cancer cells with depleted SETD7 expression were subjected to more severe oxidative stress." (PMID 29212211, 2017). "Increasing studies have confirmed that SETD7 plays a crucial role in regulating cancers." (PMID 41203594, 2025). "This shows that the expression and role of particular PMTs like SETD7/9 may vary across different cancers at various stages." (PMID 38827317, 2024). "SETD7 has been identified to be a key oncogene in cancer development 11-13." (PMID 38904013, 2024). "We focus on the role of SETD7 in cancers, and speculate on the possible points of intervention and areas for future research." (PMID 35812730, 2022).
cancer (continued). "However, its role in cancer is far from clear as SETD7 expression and activity have been related to both tumour-suppressing and tumour-promoting effects." (PMID 35326563, 2022). "(R)-PFI-2 also increased the sensitivity of primary-patient derived non-small LCa cells to doxorubicin, thus supporting the idea that SETD7-selective inhibitors could be used to enhance anti-cancer therapy." (PMID 35326563, 2022). "Finally, SETD7 has a consensus role in promoting the differentiation process of several healthy tissues and this role is maintained consistently in cancer cells by inhibiting EMT." (PMID 35326563, 2022). "Additionally, in MCF-7 cells, SETD7 knockdown induced the purported cancer stem-like cell phenotype (CD44+/CD24−/low) and dedifferentiation of mammospheres associated with loss of cadherin-1." (PMID 35326563, 2022). "We saw that SETD7 is differentially expressed across subtypes, which may determine how SETD7 modulates cancer cell biological processes in each subtype." (PMID 36551516, 2022). "Moreover, signalling pathways, miRNAs and chemical compounds were found to regulate SETD7 expression in different cancers." (PMID 35326563, 2022). "Moreover, there are several SETD7 inhibitors currently available and some studies have suggested SETD7 inhibition as a potential anti-cancer therapy." (PMID 35326563, 2022). "It remains to be explored whether SETD7 has tissue-specific effects on regulating the growth of cancer cells." (PMID 35600335, 2022). "Thus, DNMT1 methylation by SETD7 can be addressed as an interesting process to be explored in the development of new therapeutic strategies, particularly for cancer treatment." (PMID 30013796, 2018). "While the specific connection between SETD7 and cellular metabolomics remains an active area of research, understanding its role in these processes could shed light on novel therapeutic strategies for cancer and other diseases." (PMID 39522095, 2024). "Therefore, ER or AR combines with SETD7 might serve as the panel of prognostic markers or therapeutic targets for patients with such cancers." (PMID 35812730, 2022). "In the future and based on previous findings showing that inhibition of SETD7 in other types of cancer improves response to chemotherapy, it would be interesting to explore if this subgroup of patients could benefit from targeting SETD7 with inhibitors to improve chemotherapy response." (PMID 36551516, 2022). "Finally, the significance of SETD7 in the endoplasmic reticulum (ER) stress response and in cancer development and progression are discussed, and the potential of this enzyme for targeted cancer treatment is highlighted." (PMID 30013796, 2018). "Further understanding SETD7’s effects in disease conditions will help determine whether stimulating or inhibiting SETD7 activity in particular cell signaling contexts represents an effective approach for the treatment of cancer." (PMID 30013796, 2018). "Hence, SETD7 may play a critical role in several physiological and pathological processes, such as metabolism, immunity and cancer." (PMID 30013796, 2018). "The subcutaneous inoculation of cancer cells enabled us to investigate the cytotoxic efficacy of CPH on the growth of tumors at the inoculation site and to assess the role of Setd7 in regulating metastasis to the lungs." (PMID 39522095, 2024). "eL29 has been identified as a major substrate for methylation by Set7/9 (also known as Set7, Set9, Setd7 or Kmt7), which is a modulator of the Hippo/YAP and Wnt pathways in many cancers." (PMID 38989007, 2024). "As a crucial biomarker of cancers, which is now a hot spot in current research in cancer, the methylation site of YAP1 by SETD7 deserves further investigation." (PMID 38670954, 2024). "The authors highlight three PKMTs – SETD2, SETD7, and EZH2 – which have been found to suppress tumor growth in various types of cancer." (PMID 38036730, 2023).
cancer (continued). "In particular, SETD7, EZH2, G9a, SMYD2 and SUV4-20H2 have been extensively studied in cancer, and these proteins are being pursued as therapeutic targets of anticancer drugs." (PMID 38036730, 2023). "Two studies performed in cell lines from different cancer types (BC and CRC) showed that knockdown of SETD7 decreases Nrf-2, consequently decreasing its target genes and increasing ROS accumulation and apoptosis." (PMID 35326563, 2022). "All studies showed that, independently of the type of cancer (BlaCa, BC, CRC, GC, HCC and LCa), knockdown of SETD7 by siRNAs or the inhibition of its activity by (R)-PFI-2 promoted EMT and consequently invasion, migration and eventually metastasis." (PMID 35326563, 2022). "Taken together, these data suggest that the ISL1/SETD7 complex directly binds to the ZEB1 promoter to activate its expression in gastric cells, which consequently leads to cancer tumorigenesis in GC." (PMID 30674889, 2019). "SET domain-containing 7 (SETD7, also known as KMT7 or SET7/9), a histone lysine methyltransferase (HKMT) responsible for catalyzing histone H3 lysine 4 monomethylation (H3K4me1), has emerged as a key regulator in multiple cancers." (PMID 41203594, 2025). "Studying the anti-cancer effects of CPH in SETD7 KO in vitro and in vivo models may help unravel the correlation between SETD7 inhibition and CPH anti-cancer effects." (PMID 39522095, 2024). "SETD7 is a significant modifier of multiple non-histone proteins and exerts either tumor-suppressive or oncogenic functions in various cancer types." (PMID 39725038, 2024). "To date, there is no consensus regarding SETD7 ́s biological functions, or potential for cancer diagnostics and therapeutics." (PMID 35326563, 2022). "A lysine methyltransferase, SETD7, has multiple histone and non-histone substrates that have been explored for targeted treatments of conditions, such as cancer and obesity." (PMID 35115604, 2022). "Actually, the roles of SETD7 and KLF4 in cancers are controversial." (PMID 32126149, 2020). "SETD7 involvement in cancer is evident and its function is relevant for several cancer-related processes, but no consensus regarding its theragnostic potential in cancer can be inferred." (PMID 35326563, 2022). "However, the expression levels of KHDRBS1 or SETD7 alone did not display any statistically significant correlation with survival rates of cancer patients." (PMID 35326563, 2022). "Thus, in normal conditions, SETD7 targets HIF-1α for degradation operating as a tumour suppressor, but in oxidative stress, SETD7 exerts tumour-promoting effects by maintaining redox homeostasis to protect cancer cells from apoptosis." (PMID 35326563, 2022). "However, studies on SETD7 in cancer research have long focused on its non-histone substrates." (PMID 41203594, 2025).
tumor (50 papers, 2012 to 2025). "Only one mutation in a SETD7 lysine methylation site was found, consisting of a K873E missense mutation in the tumour suppressor RB1, in only one sample." (PMID 36551516, 2022). "SETD7 expression appears strongly associated with tumour stromal and immune signatures and related to therapy resistance." (PMID 36551516, 2022). "High SETD7-expressing tumours further exhibited a higher rate of ERBB2 mutation (20% vs. 5%) along with a poorer response to anti-Her2 therapy." (PMID 36551516, 2022). "A relationship between SETD7 expression and prognosis was consistent only for patients with basal-like tumours, where high-SETD7 was significantly associated with worse RFS, DMFS, and OS." (PMID 36551516, 2022). "Statistical analyses were conducted to associate SETD7 expression with tumor features and patient outcomes, as well as related proteins expression." (PMID 27183310, 2016). "Univariate and multivariate analysis revealed that high SETD7 expression, large tumor size and metastasis are associated with reduced OS." (PMID 27183310, 2016). "Increased SETD7 is associated with metastasis, recurrence, large tumor size, and poor tumor differentiation, and indicates poor prognosis in HCC patients." (PMID 27183310, 2016). "Furthermore, SETD7 has tumor suppressor activity in PCa cells, and deletion of SETD7 expression is significantly associated with PCa progression and tumor aggressiveness." (PMID 38605023, 2024). "SETD7 protein expression was positively associated with tumour size and grade and nodal status." (PMID 35326563, 2022). "This differential SETD7 expression may be related to the higher frequency of SETD7 gene loss that we noted for the basal-like subtype and, to some extent, the low-level gain of SETD7 that we observed among the Her2-enriched subtype tumours." (PMID 36551516, 2022). "The expression level of SETD7 in liver cancer tissue is significantly increased and is closely related to the pathological stage and size of the tumor." (PMID 41203594, 2025). "By regulating the ERK/MAPK signaling pathway, SETD7 promotes epithelial-mesenchymal transition and tumor cell migration in triple-negative breast cancer." (PMID 41203594, 2025). "The results demonstrated that SETD7 knockdown significantly inhibited tumor growth compared to controls, evidenced by reduced tumor volume and weight." (PMID 41203594, 2025). "Due to the aberrant expression of SETD7 in tumor cells and its high correlation with a bad prognosis for patients with tumors, new inhibitors of SETD7 have been developed as possible therapeutic medicines." (PMID 39602041, 2025). "Given the role of ferroptosis in regulating tumor progression, we prioritized investigating SETD7’s regulatory role in ferroptosis." (PMID 41203594, 2025). "To further investigate the pro-tumor effect of SETD7, we assessed the expression of epithelial-mesenchymal transition (EMT) markers." (PMID 39725038, 2024). "Mmp1a, Mmp3, and Mmp13, which engage in metastasis through facilitating invasion of tumor cells, were downregulated in Setd7 KO and CPH groups compared to Setd7 WT group." (PMID 39522095, 2024). "Our data suggest that SETD7 plays a potent tumor-promotive role in OC cells via modulating LC3B methylation and degradation." (PMID 39725038, 2024). "To confirm these results in vivo, we successfully constructed a stable CAKI-1 cell line that knocked down SETD7 and then performed tumorigenesis and tumor metastasis assay in nude mice." (PMID 38904013, 2024). "Our analysis of in vivo tumor tissues by RT-qPCR showed Setd7 KO and CPH-treated mice showed attenuated apoptotic and metastatic pathways such as Akt/mTOR and MMPs." (PMID 39522095, 2024). "SET domain containing 7(SETD7), a member of histone methyltransferases, is abnormally expressed in multiple tumor types." (PMID 38904013, 2024). "First, we investigated the efficacy of Setd7 inhibitor CPH on the growth of the LLC1 primary tumor in Setd7 WT mice." (PMID 39522095, 2024).
tumor (continued). "SETD7 aided tumor cell growth and inhibited apoptosis, as well as sensitively maintaining redox equilibrium by controlling GSH/GSSG and ROS levels." (PMID 37602329, 2023). "The role of SETD7 in BCa immune escape was validated by analyzing the correlation between SETD7 expression and tumor microenvironment (TME)-related indicators." (PMID 37564199, 2023). "Half of these studies identified SETD7 as a tumour promoter and the other half as a tumour suppressor." (PMID 35326563, 2022). "ApcMin/+/Setd7−/− mice had significantly increased lifespans and reduced tumour numbers in the small intestine and colons at endpoint compared with littermate control ApcMin/+/Setd7+/− mice." (PMID 35326563, 2022). "In summary, the two studies described that tumour-suppression by SETD7 results from its methylation of oncogenic proteins leading to their degradation." (PMID 35326563, 2022). "Together, these results indicate that SETD7 has a tumour-suppressing role in BC cells possibly by inhibiting aberrant expression of E2F1 and DNMT1." (PMID 35326563, 2022). "Several studies support a tumour-promoting role of SETD7 through the analysis of in-house cohorts and databases." (PMID 35326563, 2022). "The same authors analysed a cohort of 68 HCC tissues compared to the paired adjacent healthy tissues by IHC, and found SETD7 significantly correlated with pathological stage and tumour size." (PMID 35326563, 2022). "Most of the patients who received chemotherapy only had basal-like (~60%) or Her2+ (~40%) tumours and, interestingly, high SETD7 was correlated with worse RFS or DMFS (not shown) only for patients with the basal-like subtype." (PMID 36551516, 2022). "Only two genes (GPER1 and CYP4F22) were oppositely correlated with SETD7 expression in different subtypes, being enriched in in low-SETD7 tumours for all subtypes except luminal B where they were upregulated in the high-SETD7 group." (PMID 36551516, 2022). "Wnt-target gene (Axin2, Myc and Lgr5) expression was increased in the small intestine tumour tissue compared to normal tissue from both ApcMin/+/Setd7−/− and ApcMin/+/Setd7+/− mice, but more in tumours from ApcMin/+/Setd7+/−." (PMID 35326563, 2022). "Higher SETD7 mRNA and protein in Her2-enriched tumours was correlated with increased ERBB2 amplification and corresponding ERBB2 mRNA upregulation." (PMID 36551516, 2022). "Regarding luminal tumours, high SETD7 was also correlated with worse RFS, but only in patients receiving endocrine therapy and this association was not sufficiently strong, as the ROC plot did not support a prognostic value." (PMID 36551516, 2022). "SETD7 overexpression increased cell proliferation and decreased apoptosis while the opposite was observed if SETD7 was knocked down and rescued the miR-345-5p anti-tumour effects." (PMID 35326563, 2022). "Like many histone-modifying enzymes, SETD7 plays a key role in cell proliferation and inhibits tumour cell differentiation." (PMID 35600335, 2022). "In conclusion, strong evidence suggests that expression of SETD7 is predictive of a poor outcome for patients carrying basal-like tumours, even though this subtype has lower SETD7 expression in comparison to the luminal A or Her2-enriched subtypes." (PMID 36551516, 2022). "A list of 83 genes, including the 42 known SETD7 targets plus other genes reported to be associated with SETD7 function, was used to query the genes differentially expressed in high- versus low-SETD7 tumours for each subtype." (PMID 36551516, 2022). "SETD7 exhibits it impact as either an oncogenic protein or a tumor suppressor, thus, SETD7 is emerging as a therapeutic target in YAP-, ER-, AR-, and GLI3-mediated tumorgenesis." (PMID 35812730, 2022). "The m6A modification catalysed by METTL3 is recognized by YTHDF2 to mediate the mRNA decay of tumour suppressors SETD7 and KLF4, which consequently induces the BCa progression." (PMID 32126149, 2020).